CDKN2B (cyclin dependent kinase inhibitor 2B)
Diseases named in the same sentence as CDKN2B in open-access papers (continued):
Sharing a sentence is not in itself a finding about the gene and the disease.
type 2 diabetes (15 papers, 2009 to 2025). "The genomic region at 9p21 chromosome near the CDKN2A/CDKN2B genes is associated with type 2 diabetes(T2D) and cardiovascular disease(CVD)." (PMID 23134948, 2012). "Thus, as with the Hhex-Ide locus, these studies cannot distinguish whether Cdkn2a or Cdkn2b is the causative gene, and actually suggest a role for both in the development of type 2 diabetes." (PMID 23442068, 2013). "We identified fourteen type 2 diabetes-associated genes discovered by the first waves of GWAS for which there was little prior evidence of their potential role in diabetes (Adam30, Adamts9, Camk1d, Cdc123, Cdkal1, Cdkn2a, Cdkn2b, Ext2, Hhex, Ide, Jazf1, Lgr5, Thada and Tspan8)." (PMID 23442068, 2013). "These genes included CDKN2B, located in one of the most robust genetic markers for type 2 diabetes, CAD, and myocardial infarction." (PMID 39527631, 2024). "We confirmed the associations of genetic variations in SLC30A8, CDKN2A/CDKN2B, KCNQ1, CENTD2 with type 2 diabetes." (PMID 25587982, 2015). "We confirmed associations of SNPs in KCNQ1, CDKN2A/CDKN2B, CENTD2 and SLC30A8 with type 2 diabetes in Han Chinese." (PMID 25587982, 2015). "Evidence from previous GWA studies suggest cell cycle dysregulation as a common mechanism in type 2 diabetes; for example, type 2 diabetes association signals are found close to the cell cycle regulator genes, CDKN2A/CDKN2B and CDKAL1." (PMID 25211022, 2014). "In addition, the current study also replicated the significant associations of two other genes (CDKN2A/CDKN2B and SLC30A8) with type 2 diabetes susceptibility, which was consistent with the observations from other studies in Han Chinese." (PMID 25587982, 2015). "This study examined the association of the polymorphic markers of the genes KCNJ11, SLC30A8, CDKAL1, CDKN2B and FTO with type 2 diabetes mellitus in Russia." (PMID 28717589, 2017). "Furthermore, in AS and type 2 diabetes, the mRNA levels of CDKN2A (p16Ink4a), CDKN2B (p15Ink4b), and CDKN2BAS are reduced." (PMID 39519014, 2024). "The association of type 2 diabetes mellitus (T2DM) with the KCNJ11, CDKAL1, SLC30A8, CDKN2B, and FTO genes in the Russian population has not been well studied." (PMID 28717589, 2017). "Sites annotated to 10 candidate genes for type 2 diabetes, including DUSP9, BCL11A, HNF4A, and CDKN2B, and 7 candidate genes for related metabolic traits (for example, ATP11A, ADCY5 and IRS1) had differential DNA methylation in human pancreatic islets based on sex." (PMID 25517766, 2014).
diabetes (14 papers, 2010 to 2024). "The mRNA expressions of GCK, GCKR, GLIS3 and CDKN2B, known to be related to diabetes mellitus, were examined by RT-PCR." (PMID 37049638, 2023). "Dietary habits influence the association of six genes (C2CD4B, CDKN2B, GIPR, HHEX, SLC2A2, and SLC30A8) forming the third cluster with diabetes, adipogenesis, and cardiovascular risk." (PMID 36982283, 2023). "In murine models, overexpression of Cdkn2a leads to decreased islet proliferation in aging mice and that of Cdkn2b leads to islet hypoplasia and diabetes." (PMID 33017871, 2020). "Several diabetes-related or inflammation-related genes are included in the TG-associated pathways, such as SMAD3, TGFB1, CDKN2B, and IL10." (PMID 26308950, 2015). "In addition, isolated compounds 3, 4, 6 and 7 had an effect that significantly changed the mRNA expressions of GCK, GCKR, GLIS3 and CDKN2B, which are related to diabetes mellitus in the alloxan-induced zebrafish." (PMID 37049638, 2023). "The SNPs in 3′UTR of miRNA target genes reported in diabetes include rs11724758 in FABP-2; rs1046322 in WFS-1; rs2229295 in HNF1B; rs1063192 in CDKN2B; and rs13702 in LPL genes." (PMID 34925466, 2021). "This is thought to be due to the CDKN2A and CDKN2B genes in this genomic region inhibiting CDK4 and CDK6, which has been demonstrated to influence β cell proliferation and mass, eventually leading to diabetes." (PMID 25430018, 2014).
bladder cancer (13 papers, 2001 to 2025). "The only common deletion concerns locus 9p21.3 which encompasses genes CDKN2A and CDKN2B encoding for tumor suppressors p14ARF and p15INK4b and occurs in 31.9% of bladder carcinomas." (PMID 35323317, 2022). "CDKN2A and CDKN2B are located on chromosome 9p, and commonly deleted in bladder cancer, as well as other cancer types." (PMID 31857723, 2020). "The expression levels of hsa-miR-429 and cyclin-dependent kinase inhibitor 2B (CDKN2B) were determined using Real-Time qPCR in a total of 50 patients with bladder cancer." (PMID 28978151, 2017). "In consistent with the prediction, we showed that hsa-miR-429 and CDKN2B were inversely expressed in bladder cancer." (PMID 28978151, 2017). "In this study, we identified that overexpression of hsa-miR-429 is a novel contributor to the down-regulation of CDKN2B in bladder cancer, suggesting that post-transcriptional inhibition plays roles in repressing CDKN2B expression." (PMID 28978151, 2017). "The relative expression levels of Hsa-miR-429 and CDKN2B were evaluated using Real-Time qPCR in 50 patients with bladder cancer." (PMID 28978151, 2017). "EdU incorporation assay was also used as a further study to determine the effects of CDKN2B siRNA/hsa-miR-429 mimic on proliferation of bladder cancer cell lines." (PMID 28978151, 2017). "As revealed by ELISA assay, decreased cell apoptosis was observed in both bladder cancer cells by transfection of hsa-miR-429 mimic or CDKN2B siRNA." (PMID 28978151, 2017). "In conclusion, overexpression of hsa-miR-429 contributes to the underexpression of CDKN2B in bladder cancer." (PMID 28978151, 2017). "Hsa-miR-429 also promotes bladder cancer cell proliferation by inhibiting CDKN2B." (PMID 40002643, 2025). "It is noteworthy that the deletion of CDKN2A and CDKN2B, key regulators of Cdk4/6 expression, occurs in ~50% of bladder cancers, as this indicates that many MI-BC patients may be responsive to Cdk4/6 inhibitors." (PMID 30875757, 2019). "The data also reveal that the expression levels of CDKN2B were decreased in bladder cancer." (PMID 28978151, 2017). "CDKN2B was decreased in bladder cancer compared with matched normal urothelium." (PMID 28978151, 2017). "Hsa-miR-429 and CDKN2B were inversely expressed in bladder cancer." (PMID 28978151, 2017). "Bladder cancer T24 and 5637 cells were transfected CDKN2B siRNA or hsa-miR-429 mimic." (PMID 28978151, 2017). "Hsa-miR-429 promotes bladder cancer development via down-regulating CDKN2B." (PMID 28978151, 2017). "Down-regulation of CDKN2B promoted bladder cancer cell proliferation and decreased apoptosis." (PMID 28978151, 2017). "We hypothesized that hsa-miR-429 may play oncogenic roles via inhibiting CDKN2B in bladder cancer." (PMID 28978151, 2017). "Promoter methylation at CDKN2B/p15 is not frequent in bladder cancer, as previous studies have reported a methylation frequency ranging from 0-13%." (PMID 24790823, 2014).
acute lymphoblastic leukemia (12 papers, 2015 to 2024). Leukemia with an acute onset, characterized by the presence of lymphoblasts in the bone marrow and the peripheral blood. "Recurrent deletions of the CDKN2A/ARF/CDKN2B genes encoded at chromosome 9p21 have been described in both pediatric and adult acute lymphoblastic leukemia (ALL), but their prognostic value remains controversial, with limited data on adult T-ALL." (PMID 30041662, 2018). "The genes CDKN2A and CDKN2B (encoding the tumor suppressors p15, p16 and p19) are commonly deleted or hypermethylated in T-cell acute lymphoblastic leukemia (ALL)." (PMID 25917288, 2015). "It is important to note that the prognostic significance of homozygous CDKN2A/CDKN2B deletions is limited to cortical and mature T-cell acute lymphoblastic leukemia (T-ALL)." (PMID 39408811, 2024). "The locus CDKN2A/B (9p21.3), which comprises the tumor suppressors genes CDKN2A and CDKN2B and the long noncoding RNA (lncRNA) known as ANRIL (or CDKN2B-AS), was associated with childhood acute lymphoblastic leukemia (ALL) susceptibility in several genome wide association studies (GWAS)." (PMID 28481918, 2017). "A total of 45%–48% of B cell precursor acute lymphoblastic leukemia (BCP-ALL) PDX models contain canonical focal deletions of the tumor suppressors on chromosome 9p, CDKN2A or CDKN2B, the majority of which are homozygous." (PMID 31693904, 2019).
colon cancer (12 papers, 2010 to 2025). "Previous studies have identified that there is a high frequency of methylation in the promoter of CDKN2B, leading to the downregulation of CDKN2B in colon cancer." (PMID 25202407, 2014). "It has been reported that TSA can activate certain hypermethylated genes, including CDKN2B, CDKN2A, MLH1 and TIMP3 in colon cancer cells after Dnmt1 inhibition by DNA demethylating agent such as 5-aza-dc." (PMID 32334468, 2020). "For example, poor prognosis was reported to be associated with low DLC1, low CDKN2A/B and high CDK4 in lung cancer, and low DLC1, low CDKN2B, and high CDK6 in colon cancer." (PMID 25425654, 2014). "Studies of lung and colon cancer show that underexpression of DLC1 frequently co-occurs with deregulated expression of cell cycle genes such as CDK6, CDK4, CDKN2A, and CDKN2B." (PMID 25425654, 2014).
coronary artery disease (12 papers, 2007 to 2025). "Of the 78 peaks linked to 59 genes through all three approaches, interesting candidate regulatory elements include four peaks linked to CDKN2B, whose gene product has known roles in cell cycle control and whose regulation has been linked to coronary artery disease." (PMID 34699533, 2021). "Moreover, it interacts with CDKN2B (cyclin-dependent kinase inhibitor 2B), whose expression was found to be induced by TGF-β and is associated with coronary heart disease." (PMID 33081147, 2020).
glaucoma (12 papers, 2012 to 2025). Increased pressure in the eyeball due to obstruction of the outflow of aqueous humor. "CDKN2B is expressed in human iPSC‐derived RGCs,32 and the CDKN2B gene variants are associated with primary angle open glaucoma." (PMID 39021340, 2024). "CDKN2B/CDKN2A encodes tumor suppressor proteins p16INK4A/p15INK4B which influences cell proliferation/senescence in RGCs, the degeneration of which is a risk factor for glaucoma." (PMID 33397358, 2021). "In this meta-analysis, we combined data from included studies to evaluate genetic association between CDKN2B gene rs1063192 polymorphism and glaucoma." (PMID 28416752, 2017). "Recently, a host of studies explored the association between CDKN2B gene rs1063192 polymorphism and glaucoma risk." (PMID 28416752, 2017). "In this meta-analysis, our data indicated that CDKN2B gene rs1063192 polymorphism with the decreased risk of glaucoma." (PMID 28416752, 2017). "Meta-analysis showed that CDKN2B gene rs1063192 polymorphism was associated with a decreased risk of glaucoma." (PMID 28416752, 2017). "In conclusion, this meta-analysis indicates that CDKN2B gene rs1063192 polymorphism is significantly associated with a decreased risk of glaucoma." (PMID 28416752, 2017). "GWAS studies for glaucoma showed direct association of CDKN2B region of 9p21 locus with glaucoma, identifying its significance as a risk factor." (PMID 28416752, 2017). "Recent genome-wide association studies (GWASs) have identified several genetic variants associated with glaucoma, including cyclin-dependent kinase Inhibitor-2B (CDKN2B) gene." (PMID 28416752, 2017). "In conclusion, this meta-analysis demonstrates that CDKN2B gene rs1063192 polymorphism is significantly associated with a decreased risk of glaucoma." (PMID 28416752, 2017). "The aim of this meta-analysis was to evaluate the association between cyclin-dependent kinase Inhibitor-2B (CDKN2B) gene rs1063192 polymorphism and glaucoma risk." (PMID 28416752, 2017). "It is reported to be upregulated in response to elevated IOP in animal model of glaucoma suggesting apoptosis of RGCs may be promoted due to altered expression of CDKN2B and cause glaucomatous visual field loss." (PMID 33397358, 2021). "CDKN2B is a tumor suppressor gene involved in cell signaling pathways and polymorphisms in this gene have been associated with various diseases, including multiple cancers, gestational diabetes mellitus, familial combined hyperlipidemia and glaucoma." (PMID 32492046, 2020). "Therefore, we conducted this comprehensive meta-analysis to demonstrate the association between CDKN2B gene rs1063192 polymorphism and glaucoma susceptibility." (PMID 28416752, 2017). "Therefore, we performed a comprehensive meta-analysis to clarify the possible association between CDKN2B gene rs1063192 polymorphism and glaucoma risk." (PMID 28416752, 2017). "The result of stratification analysis among Africans should be interpreted with caution, because the racial stratification of CDKN2B gene rs1063192 polymorphism and glaucoma regarding Africans included only three studies, which is insufficient to provide conclusive evidence." (PMID 28416752, 2017). "These epigenetic changes suppress the transcription of nearby tumour-suppressor genes CDKN2A and CDKN2B, thereby linking upstream signals to downstream cell cycle and stress response pathways relevant to both glaucoma and CVD." (PMID 40722690, 2025). "Background/Objectives: The INK4 locus at chromosome 9p21.3, encoding CDKN2A, CDKN2B and the long non-coding RNA CDKN2B-AS1 (ANRIL), has been implicated in multiple diseases, including glaucoma and cardiovascular disease." (PMID 40722690, 2025). "Based on the gene profiling in the optic nerve head tissue, Cadm2, Cdkn2b, and Tmtc2 exhibit altered expression very early and across all stages of glaucoma (early to severe)." (PMID 29891935, 2018).
glaucoma (continued). "Here we have identified a set of genes in POAG-associated loci whose expression is altered in the RGCs (e.g., Ank, Cadm2, and Six6) and the optic nerve head (e.g., Cadm2 and Cdkn2b) in a mouse model of glaucoma." (PMID 29891935, 2018). "Larger scale studies of populations with different ethnicities are necessary to explore the roles played by this SNP of CDKN2B gene during the pathogenesis of glaucoma." (PMID 28416752, 2017). "Sixth, CDKN2B gene rs1063192 polymorphism would be not enough to explain the associations between CDKN2B gene and glaucoma risk." (PMID 28416752, 2017). "Lastly, utilizing the linked glaucoma variant (rs1063192) in the 3'UTR of CDKN2B, we performed allele‐specific qPCR to test whether the alteration of YY1 binding by rs6475604 would affect p15INK4B expression." (PMID 37345431, 2023). "A meta-analysis using data from six independent studies comprising 3,161 glaucoma cases and 42,837 controls found evidence for rs190004 (near ATOH7), rs1063192 (in CDKN2B and the overlapping gene CDKN2B-AS1) and rs10483727 (near SIX1 gene) significantly associated with POAG." (PMID 22761751, 2012). "However, the SNP of CDKN2B rs3217992 in patients with glaucoma has not been genotyped until now." (PMID 32492046, 2020).
hepatocellular carcinoma (12 papers, 2013 to 2023). A malignant tumor that arises from hepatocytes. "In this study, we explored the function and mechanism of CDKN2B genes in verapamil (VER)-induced reversal of resistance to doxorubicin (ADM) chemotherapy in hepatocellular carcinoma (HCC)." (PMID 29299129, 2017). "Furthermore, we proved that CDKN2B inhibition of RB1 signaling promoted apatinib resistance in hepatocellular carcinoma." (PMID 37781033, 2023). "Besides, the increase in CDKN2B expression has been shown to increase the sensitivity of hepatocellular carcinoma to sorafenib." (PMID 33773557, 2021). "In the case of hepatocellular carcinoma, reduced expression of CDKN1A and CDKN2B is connected with the EMT process, migration, and cell cycle progression." (PMID 34944712, 2021).
lymphoma (10 papers, 2012 to 2022). A malignant (clonal) proliferation of B- lymphocytes or T- lymphocytes which involves the lymph nodes, bone marrow and/or extranodal sites. "These analyses indicate that EZH2 (PRC2) can promote growth of lymphoma cells via suppression of cdkn2b and/or cdkn2a." (PMID 32850364, 2020). "MYCV394D is unable to repress wild-type MYC targets such as Cyclin Dependent Kinase Inhibitor 1A (CDKN1A/p21CIP) and Cyclin Dependent Kinase Inhibitor 2B (CDKN2B/p15INK4B), in a transgenic lymphoma model." (PMID 28505071, 2017).
chordoma (9 papers, 2008 to 2025). Chordomas are rare malignant tumors arising from embryonic remnants of the notochord in axial skeleton. "The loss of the latterputative genes, CDKN2A and CDKN2B, was identifiedin 70% of classical chordoma biopsies evaluated with bacterial artificialchromosome (BAC) array CGH." (PMID 21602918, 2011). "Additionally, homozygous deletions of CDKN2A and CDKN2B genes, which are common in chordoma, suggest potential susceptibility to CDK4/6 inhibitors." (PMID 39941902, 2025). "Other frequent deletions reported in chordoma occur in the CDKN2A and CDKN2B loci, both on chromosome 9p21, which encode the cyclin-dependent kinase inhibitors known as p16 and p15, respectively." (PMID 23662285, 2013). "Copy number gains/losses present in more than ≥50% of patients of well-known cancer associated genes for example CDKN2A, CDKN2B, RAF1 and PTEN were found and may play an important role in chordoma development." (PMID 23533570, 2013). "However, the CDKN2A and CDKN2B loci in 9p21 were homo- or heterozygously lost in 70% of the tumours, a finding corroborated by fluorescence in situ hybridisation, suggesting that inactivation of these genes constitute an important step in chordoma development." (PMID 18071362, 2008). "The genetic alteration (deep deletion) frequency showed that 1/3rd of the chordoma samples have MTAP loss and CDKN2A, CDKN2B and CDKN2C loss; however, there is no loss in the folate pathway genes in the samples analyzed in personalized oncogenomics cBioPortal." (PMID 37147496, 2023).
myocardial infarction (9 papers, 2011 to 2025). Gross necrosis of the myocardium, as a result of interruption of the blood supply to the area, as in coronary thrombosis. "For example, rs10757278 near CDKN2A/CDKN2B has been robustly associated with myocardial infarction (MI)." (PMID 23382687, 2013). "A region on chromosome 9p21.3, within the CDKN2B anti-sense RNA (CDKN2B-AS1), nearby the CDKN2A and CDKN2B genes, has been found to be strongly associated with CHD and myocardial infarction." (PMID 25185447, 2014). "Similar to the PAR of this KIF3A variant, the PAR for myocardial infarction was 21% in individuals with the previously reported rs10757278 variant located in adjacent CDKN2A and CDKN2B genes." (PMID 21912604, 2011).
myelodysplastic syndrome (8 papers, 2009 to 2025). A clonal hematopoietic disorder characterized by dysplasia and ineffective hematopoiesis in one or more of the hematopoietic cell lines. "Methylation changes in the 9p21 chromosomal regions consisting of the cyclin-dependent kinase inhibitor 2B (CDKN2B) and cyclin-dependent kinase inhibitor 2A (CDKN2A) genes have been frequently associated with myelodysplastic syndromes and AML." (PMID 34358067, 2021).